CDK2 (cyclin dependent kinase 2)
Diseases named in the same sentence as CDK2 in open-access papers (continued):
Sharing a sentence is not in itself a finding about the gene and the disease.
tumor (continued). "Common to all tumor cells analysed, cdk2 and cyclin A were distinctly suppressed by VPA." (PMID 29299126, 2017). "Of significance, specific cyclinE/ CDK2 inhibitors can block tumor progression." (PMID 28467776, 2017). "However, the tumor suppressing roles of miR372 was also found in some cancer cells, possibly via the down-regulation of CDK2 and CCNA1." (PMID 28467776, 2017). "All three cell lines could form tumours in mice, but R50 grew markedly more slowly than WT and CDK2−/− tumours." (PMID 29222471, 2017). "Therefore we evaluated the particular role of the cdk2-cyclin A axis in tumor growth control by blocking their function using siRNA." (PMID 29299126, 2017). "Moreover, CDK2 has been reported to be essential for cell proliferation in several human tumours and emerging data have suggested that CDK1 or CDK2 can be considered as the most appropriate CDKs to target in combination with DNA-damaging agents." (PMID 27898692, 2016). "Cyclin-dependent kinase 2 (CDK2) has been reported to be essential for cell proliferation in several human tumours and it has been suggested as an appropriate target to be considered in order to enhance the efficacy of treatment regimens based on the use of DNA damaging drugs." (PMID 27898692, 2016). "Besides, different from CCNB1, CCNA1 functions in S and G2/M phases, which is due to its two different phosphorylated substrates, CDK1 and CDK2, subsequently conducing tumor cells proliferation." (PMID 26999101, 2016). "Cdk2 and cyclin E were inversely correlated with tumor mass, as was immunoprecipitated Rb." (PMID 27077880, 2016). "Additionally, survival probabilities were significantly lower in tumor with high expression of cdk2 (p = 0.006), cdk4 (p = 0.003) or cdk6 (p = 0.045)." (PMID 26029996, 2015). "Moreover, inactivation of cdk2 is synthetic lethal in MYCN-amplified tumor cells and cdk2 was also proposed as a potential target for NB therapy." (PMID 26029996, 2015). "We observed that TQ inhibited tumor cell growth in vitro, where treatment with TQ arrested the cell cycle in G1 by upregulating p21 and downregulating cyclinD1 and CDK2 expression; moreover, TQ induced apoptosis by decreasing expression of Bcl-2 and increasing expression of Bax." (PMID 26416455, 2015). "Amygdalin, therefore, may block tumor growth by down-modulating cdk2 and cyclin A. In vivo investigation must follow to assess amygdalin's practical value as an anti-tumor drug." (PMID 25136960, 2014). "Suppression of cdk2 and cyclin A might be one relevant mechanism defining how amygdalin may arrest or diminish tumor proliferation." (PMID 25136960, 2014). "It has been shown that CDK2-dependent expression of anti-apoptotic protein XIAP may account for the inefficient apoptosis in tumor cells including Bcr-Abl expressing cells." (PMID 25360622, 2014). "Functional studies indicate that this protein may be an important cofactor for BRCA2 in tumor suppression and a modulator of CDK2 kinase activity via p21." (PMID 25330516, 2014). "Moreover, the VEGF has also been reported to activate cyclin E/Cdk2 through either ERK or PI3K/Akt signaling to modulate centrosome over-duplication in tumor endothelial cells." (PMID 24018888, 2013). "Future studies utilizing the established in vitro model, as well as genetically engineered mouse models, should be able to specifically dissect the role of Cdk2 in tumor progression, and upstream and downstream mechanisms leading to its repression and to cell cycle exit." (PMID 22548705, 2012).
tumor (continued). "In addition, involvement of furin in repression of tumor growth was also supported by decreased expression of cell proliferation related molecules (IR, cyclin D1, CDK2, and CDK4...etc)." (PMID 22808247, 2012). "Recent studies suggest that interphase CDKs (CDK4, CDK2) are only essential for proliferation of tumor cells and selective CDK inhibition may provide therapeutic benefit." (PMID 21834972, 2011). "To discover structurally different CDK2 inhibitors with improved potency and selectivity, we have designed, synthesized, and evaluated trisubstituted pyrimido[4,5-d]pyrimidines as inhibitors of tumor cell proliferation." (PMID 21886895, 2011). "Even though resistant tumor cells can escape immune recognition from γδ T cells by down regulating surface expression of MICA, γδ T cells can still be able to slow down the progression of the tumor cell proliferation by inhibiting cell cycle related molecules CDK2, CDK4 and Cyclin D1." (PMID 21935360, 2011). "It is important to recall that cell cycle control is a multifactorial system and, for example, decreased Rb expression may increase cyclin E and cdk2 which, in turn, can overcome the tumor suppressive effect of increased p27." (PMID 18840277, 2008). "The expressions of cyclin D1, cyclin E, cyclin-dependent kinase 4 (CDK4), and CDK2 were immunohistochemically examined in 90 patients with human oesophageal squamous cell carcinoma (SCC) to determine their relationship to the tumour behaviour and patient prognosis." (PMID 10390005, 1999). "However, our findings suggest that Cdk2-/- tumor cells can enhance ICD triggered by anthracyclines." (PMID 40557162, 2025). "However, it is essential to acknowledge that CDK2/4/6 inhibition may promote whole-genome duplication, potentially fueling more aggressive tumor evolution." (PMID 39605351, 2025). "Additionally, during dose escalation, PF-06873600 was investigated in tumor types that have the potential for increased cyclin E expression and/or CDK2 activity, including locally recurrent/advanced or metastatic triple-negative breast cancer (TNBC) and advanced platinum-resistant ovarian cancer." (PMID 40243688, 2025). "The data suggest that CDK2 targeting in low-CDK4/6 tumours may be a clinical strategy." (PMID 38732271, 2024). "Notably, majority targets of TB-2 are implicated in tumor therapy, including TGM2, KIT, EGFR, AURKA, FASN, and CDK2, which have garnered extensive research attention." (PMID 39376614, 2024). "We could observe that BRCA1 and BLM were also expressed higher in high-CDK2 tumours." (PMID 38732271, 2024). "Preclinical studies suggest that although proliferation of these tumors is primarily CDK4/6-dependent, resistance to CDK4/6i monotherapy might be driven by CDK2 activity, and clinical data has shown a correlation between high tumor CCNE1 mRNA levels and impaired response to combined CDK4/6i +/- ET." (PMID 38047585, 2024).
tumor (continued). "However, we did not observe the same positive correlation between EMP3 expression and CDK2 protein levels, and this may be due to the confounding effect of other upstream regulators of CDK2 activity in bulk tumor samples." (PMID 37936247, 2023). "CDK2 mRNA expression has also been shown to be upregulated in palbociclib resistant ER + cell lines, and palbociclib sensitivity may be restored by CDK2 knockdown with siRNA, resulting in tumor suppression, increased apoptosis, and senescence." (PMID 37035239, 2023). "Moreover, it has been stipulated that miR-567 could supress malignant tumour progression in NSCLC patients by regulating cyclin-dependent kinase 2 (CDK2)." (PMID 36013176, 2022). "In addition, the expression of PCNA and CDK2 was decreased by LncSIK1 in the tumour." (PMID 35092119, 2022). "Based on the EPIC algorithm, CCNA2 and CDK2 expression levels in SARC were negatively correlated with the infiltration level of CD4+ T cells (cor = −0.194, P = 2.62e−03), implying that our dimers also could target CCNA2 and CDK2 to affect the tumor immunity in MG-63 cells." (PMID 36325324, 2022). "Furthermore, the xenograft tumor-bearing mice models were established, and we proved that knock-down of PD-L1 inhibited Cyclin D1 and CDK2 (P < 0.05), and Ki67, while promoted Caspase-3 and Bax expressions (P < 0.05) to facilitate cell growth in CR-GC cells in vivo." (PMID 33579380, 2021). "Because of that, the tumor immune infiltration of T cell is closely associated with the efficiency of the immune checkpoint inhibitor therapy; thus, we evaluated the impact of the expression of STAT3/CDK2/4/6 on the therapeutic outcome of immune checkpoint blockade." (PMID 33668805, 2021). "Besides CDK4, CDK2 is highly expressed in the tumor tissues of STSs." (PMID 33686022, 2021). "In addition, the mice tumor tissues were collected and prepared, and our following results indicated that the expression levels of Cyclin D1 and CDK2 (P < 0.05), and Ki67 were decreased, while Caspase-3 and Bax were increased (P < 0.05) by co-treating CR-GC cells with DB and cisplatin." (PMID 33579380, 2021). "Similarly, YTHDF1 deficiency could inhibit NSCLC cell proliferation and xenograft tumor formation by regulating the translational efficiency of cell-cycle-related genes, such as CDK2, CDK4, and cyclin D1." (PMID 34359836, 2021). "Importantly, interventional deletion of Ccne1 was associated with reduced tumour burden at late stage, while inactivation of Cdk2 had absolutely no impact on HCC progression at all." (PMID 34830835, 2021). "However, the elevated expression of most of these genes in HCC tumor tissues did not predict patient survival except CDK2 and E2F8, for which a higher expression was associated with poor survival." (PMID 32807134, 2020). "Since upregulated expression of CDK2, CCNE, DNMT1 is associated with accelerated cell cycle progression and thus tumor growth these results suggest that the tumors might have started to develop a drug resistance after initially responding to the treatment with gemcitabine." (PMID 31661013, 2019). "Therefore, up-regulation of cdk1/cyclin B and cdk2/cyclin A might be partly responsible for tumor progression after long-term temsirolimus exposure." (PMID 31167517, 2019). "We also noted that although pharmaceutical GCN5 inhibition shows potent effect alone or in combination with CDK2 inhibition, it is currently unsuitable for in vivo use as the toxicity was strong (data not shown) and that’s the reason we used genetic silencing in animal models for xenograft tumor." (PMID 31313989, 2019). "Statins inhibit tumor cells proliferation by their effect on cell cycle by blocking the transition from G1 to S phase, this arrest is mediated by downregulation of cyclin-dependent kinase-2 (CDK-2) activity, and upregulation and stabilization of CDK inhibitors p21 and p27." (PMID 30515267, 2018).
tumor (continued). "In this study, we have demonstrated that the overexpression of MAPK7 in HCCC cells could upregulate the TGF-β expression to re-activate the miR-200b-induced inhibition of EMT and restore the expression of cyclin D1 and Cdk2 to recover cell cycle arrest for the growth of tumor cells." (PMID 29084594, 2017). "The inhibition of tumor cell growth may result from G0/G1-phase cell cycle arrest induced by a decrease in the expression of cyclin D1 and cyclin-dependent kinase 2 (CDK2) expression." (PMID 28383558, 2017). "The key genes, CDK2, MCM7, and RUVBL2, have all been observed to have an increased level of expression for adolescent hosts irradiated with protons, which likely contribute to the picture of an overall environment predisposed to both oncogenesis and tumor promotion." (PMID 26253138, 2015). "To summarize, sorafenib added to sunitinib-sensitive tumour cells reduced cdk1 and cdk2 and enhanced p19 and p27 (with slight differences among the cell lines), whereas sorafenib added to sunitinib-resistant cells time-dependently elevated cdk1 and cdk2 and down-regulated p19 and p27." (PMID 25444514, 2015). "In view of connection between Apoptin and PI3K/Akt, some antitumor chemotherapeutic agents such as methotrexate or docetaxel or paclitaxel which sensitize tumor cells for apoptosis under prolonged nuclear Akt/CDK2 activation may can be used together with AD55-Apoptin to get a even better effect." (PMID 22321574, 2012). "However, cyclin E mutants unable to interact with CDK2 protected hMECs from tumor development." (PMID 22479189, 2012). "Cyclin-dependent kinases (CDKs), especially CDK-2 and CDK-1, are essential for regulating the cell cycle, cell growth, and tumor genesis." (PMID 41965404, 2026). "We also observed that MEN1-KD induced a strong reduction of the menin, Ki67, CDK2, and CDK4 expression in the xenografted tumor tissues, suggesting that menin is an oncogenic factor in BLCA cells in vivo." (PMID 40837414, 2025). "CDK2, a key regulator of the G1–S transition, is frequently dysregulated in CRC and contributes to tumor progression." (PMID 40469179, 2025). "To abolish extracellular ATP in tumor microenvironment, we overexpressed the ATP hydrolase CD39 protein in Cdk2-/- cells, and inoculated the obtained stable cell lines into C57 mice subcutaneously." (PMID 40557162, 2025). "Further, RNA-seq of BT549 cells after siKNSTRN revealed pronounced downregulation of critical cell cycle-related genes, including CDK2, CDC20, FOXM1, and E2F1, which have been documented to drive uncontrolled proliferation and tumor growth in TNBC." (PMID 41209020, 2025). "Combining CDK4/6 and CDK2 inhibitors with the CXCR1/2 antagonist, SX-682, halted B16F10 tumor growth by blocking tumor cell proliferation and increasing the anti-tumor immune response in the tumor microenvironment." (PMID 40904502, 2025). "Gene expression analysis of the GSE42977 dataset revealed significant upregulation of AURKA, CDK2, and VPS37A in MPM tumor tissues compared to normal mesothelial and lung tissues." (PMID 40180891, 2025). "In summary, we have confirmed the tumor-promoting role of the CCL15-CCR1 axis in ESCC and revealed the downstream AKT/ERK1/2/c-Jun/CDK2 pathway as a key regulatory mechanism." (PMID 40740234, 2025). "In this study, we investigated the anti-tumor mechanisms of curcumin in CRC and identified PTBP1 and CDK2 as critical downstream targets." (PMID 40469179, 2025). "This search revealed Dihydroartemisinin as the tumor suppressor by targeting CDK17,8; on the other hand, it demonstrated Imatinib9 and Bosutinib10 as potential antagonists against CDK2." (PMID 39929880, 2025).
tumor (continued). "Mechanism, CCLs regulate tumor proliferation and the immune microenvironment through Wnt, Toll-like receptor signaling pathways and kinases (such as SRC family, CDK2)." (PMID 41445742, 2025). "A key feature of these tumors was the clustering of highly proliferative tumor cells in vascular islands, where the MAPK/ERK/CDK2 signaling pathway was active, more active than in control SHP2+ tumors." (PMID 40131370, 2025). "In most tumor cells, dinaciclib blocks cell growth primarily by inhibiting CDK1 and CDK2 and promotes apoptosis by suppressing RB phosphorylation." (PMID 39800748, 2025). "Transcriptional analysis showed a marked downregulation of key genes involved in tumor cell growth and proliferation, including CDK1, CDK2, and CDK6 (up to a 31.11‐fold decrease), PLK1 (up to a 21.49‐fold decrease), and SKP2 (up to a 14.68‐fold decrease)." (PMID 41221154, 2025). "Cdk2-/- tumors are more sensitive to MTX and can promote the infiltration of immune cells into the tumor microenvironment." (PMID 40557162, 2025). "In vivo, it inhibits PKCι/ζ, downregulates the phosphorylation of CDK7 and CDK2, blocks the cell cycle at the G0/G1 phase, and induces PARP cleavage (an apoptotic marker), thereby reducing tumor cell proliferation." (PMID 41244006, 2025). "The combined therapy of lenvatinib with CDK2 inhibitors robustly induced tumor cell senescence and caused tumor growth suppression in vitro and in vivo, and dinaciclib or PF‐07104091 may be a candidate drug combined with lenvatinib for clinical therapy of ATC patients with high expression of CDK2." (PMID 39716890, 2025). "Silymarin upregulates Kip1/p27 and Cip1/p21 expression in tumors, which decreases the protein levels of CDK2, CDK4, Cyclin E, Cyclin A, and Cyclin D1, ultimately leading to tumor cell cycle arrest and reduce proliferation." (PMID 39055491, 2024). "The multivariate analysis included tumour stage and CDK4, CDK6, CDK2, cyclin D1, cyclin E1, RB1 and pRB1 protein expression." (PMID 38612869, 2024). "Among the T-cell regulatory factors, normal and tumor genes showed prominently distinct Inter-cell Interference Coordination (ICIC), with tumor gene expression higher than normal in RAN, CHK1, and CDK2 cells." (PMID 38714987, 2024). "It has been reported that simultaneous inhibition of CDK2, CDK4, and CDK6 extended control of the tumor cell cycle." (PMID 38338471, 2024). "On the other hand, it can reduce the expression of cell cycle proteins such as Cyclins B1, Cyclins D1, CDK1, CDK2, and CDK4, preventing the transition of tumor cells from the G2 phase to the M phase and inhibiting cell proliferation." (PMID 39274982, 2024). "POU4F1 is necessary for the tumor growth and malignant phenotypes of BLBC through regulating G1/S transition by direct binding at the promoter of CDK2 and CCND1." (PMID 38491910, 2024). "In this case, CDK2 and IRF1 being in the active state were the largest contributors to correctly identifying the cell state of the tumor as NPC." (PMID 38766170, 2024). "The expressions of miR-4516 were lower, while the expressions of Wnt 8B, DVL3, FOSL1, CDK1, CDK2, CCNA1, and CCNB1 were enhanced in tumor tissue compared to normal lung tissue in the human samples." (PMID 38930863, 2024). "Various therapies have been proposed specifically for CCNE1-amplified tumours, including WEE1 kinase and CDK2 inhibitors, and proteasome inhibitors." (PMID 38036971, 2023). "Cells treated with curcumin conjugated with Dox revealed the up-regulation of tumor suppressive gene RB1, and the down-regulation of cyclin-dependent kinase 2 (CDK2) confirmed cell cycle arrest at the G1 phase." (PMID 37765192, 2023). "The immunohistochemistry result of subcutaneous tumor indicated that knockdown CLSPN significantly down regulated CCNA2, CCNB1, CDK1, CDK2 and Ki67 expression." (PMID 37268895, 2023).